IL4 (interleukin 4)
Diseases named in the same sentence as IL4 in open-access papers (continued):
Sharing a sentence is not in itself a finding about the gene and the disease.
Sjögren’s syndrome (12 papers, 2013 to 2025). "However, recent data have shown that IL-4 was required to regulate the synthesis of pathogenic autoantibodies against M3R by B lymphocytes in the NOD.IL-4-gene knockout mouse model of Sjögren's syndrome." (PMID 24382973, 2013). "Our previous study pointed out that SS-1 inhibits Th1 (CD4+ IFN-γ+ and CD4+ TNF-α+ cells) and Th2 (CD4+ IL-4+ c cells) polarization of mouse spleen cells and T cell proliferation in Sjögren’s syndrome." (PMID 34200223, 2021). "On other hand, Th2-associated cytokines are only important in the case of dry eye disease (IL4, IL5, IL33) and Sjögren’s syndrome (IL33)." (PMID 31810226, 2019). "Additionally, in a Sjögren’s syndrome mouse model, TGP improved disease outcomes by modulating the Th1/Th2 cytokine balance and reducing IFN-γ, IL-4, Fas, and FasL expression." (PMID 40356896, 2025). "Unlike IgG4-RD, IL-4+ TFH cells are rarely found in tertiary lymphoid organs in Sjögren’s syndrome, a disorder in which IgG4 is not elevated." (PMID 29984361, 2018).
ZIKV infection (12 papers, 2018 to 2023). "In the present study, the C allele for IL4 rs224325 was more frequent and associated with mothers who had children with microcephaly due to ZIKV infection, which, according to the function described for this SNP, may be associated with lower levels of IL-424." (PMID 36859461, 2023). "The detection of cytokines such as IL-2, IL-4, and IL-17 in individuals in the acute phase of ZIKV infection suggests a polyfunctional response profile characterized by Th1, Th2, and Th17 responses." (PMID 37514084, 2023). "In Zika virus infection, Tfh cells enhanced the production of cytokines, such as IL-4 and IL-21, and also acted in a Th1-like manner, producing IFN-γ." (PMID 37514084, 2023). "Cytokine profiles in acute ZIKV infections were estimated using a multiplex bead analysis assay which measured interleukin (IL) 1β, IL-2, IL-4, IL-6, IL-8, IL-9, IL-10, IL-13, and IL-17." (PMID 30682026, 2019). "We show that the immune response during the acute phase of ZIKV infection is polyfunctional and broadly inflammatory, as evidenced by significantly elevated levels of IL-4, IL-17, IFN-γ, IL-1β, IL-1Ra, TNF-α, and IL-6 in patients as compared to controls." (PMID 29768624, 2018). "For example, Zika virus infection was associated with an increased secretion of IL2, IL4, IL13, and IL9 cytokines." (PMID 29937515, 2018). "Moreover, WNV and ZIKV infection each led to inhibition of pY-STAT1 and 3 in response to human and mouse IL6, and of pY-STAT6 following IL4 treatment." (PMID 32272626, 2020). "ZIKV infection triggered the upregulation of multiple cytokines in humans during acute phase of infection that we were able to characterize by Luminex assay, including IP-10, IL-5, GM-CSF, TNF-α, IL-15, IL-10, MIP-1α, IFN-γ, IL-6, IL-1RA, IL-2, MIG, IFN-α, IL-2R, and IL-4." (PMID 30333476, 2018).
allergic conjunctivitis (11 papers, 2011 to 2024). "As such, monoclonal antibody against IL-4R alpha can attenuate the IL-4 and IL-13-induced pathophysiological changes in allergic conjunctivitis." (PMID 38541674, 2024). "The development of an ophthalmic-formulated version of this drug will serve to eliminate or minimize the involvement of IL-4 and IL-13 in mediating type 2 inflammatory processes in allergic conjunctivitis." (PMID 38541674, 2024). "Several reports have shown that, following activation of Janus-kinases (JAKs) in allergic conjunctivitis, IL-4 and IL-13 induce the expression of specific genes by activating STATs." (PMID 37784129, 2023). "The present study sought to investigate the expression of TSLP and its downstream molecules IL-4, IL-13, and IL-5 in the conjunctival tissue of patients with allergic conjunctivitis and tear." (PMID 27504196, 2016). "The tear TSLP, IL-4, IL-5, and IL-13 expression levels in different types of allergic conjunctivitis were found elevated to varying degrees in the VKC, SAC, and PAC compared with the control group; the differences were statistically significant (P < 0.001)." (PMID 27504196, 2016). "Immunohistochemical staining confirmed an increase in TSLP, IL-4, IL-5, and IL-13 production in the eyes with various types of allergic conjunctivitis." (PMID 27504196, 2016). "Immunohistochemistry, real-time PCR, and Luminex technology were used to measure the expression of TSLP, IL-4, IL-5, and IL-13 in the tears and conjunctival cell of the normal population and patients with three types of allergic conjunctivitis." (PMID 27504196, 2016). "IL-4 is responsible for activating conjunctival fibroblasts to undergo proliferation, which presents clinically as papillae on the palpebral conjunctiva in allergic conjunctivitis." (PMID 38541674, 2024). "The conjunctival tissues of various types of allergic conjunctivitis displayed stronger TSLP, IL-4, IL-5, and IL-13 staining throughout the entire epithelium than did those of normal controls." (PMID 27504196, 2016). "In addition, IL-4, IFN-γ, and IL-10 were elevated in active seasonal allergic conjunctivitis and vernal keratoconjunctivitis." (PMID 35160111, 2022). "In sum, the activation of CD4+TLR4+T cells by the antigen and TLR induces an inflammatory microenvironment characterized by TNF-α, IL-6, and IL-4, which favors a lack of immune regulation in perennial allergic conjunctivitis." (PMID 33114004, 2020). "We conclude that the high levels of IL4, IL5, and IL13 that characterize allergic conjunctivitis could be the reason for higher numbers of goblet cells and mucin overproduction found in this condition." (PMID 30111832, 2018). "In light of our results, the high levels of IL4, IL5, and IL13 that characterize allergic conjunctivitis could be the reason for the increased number of goblet cells and could have a role in the mucin overproduction found in this pathological condition." (PMID 30111832, 2018). "Tanaka and Alfonso demonstrated that Sema3a suppressed the release of Th2-related cytokines (IL-5, IL-13 and IL-4) and inflammatory cytokines (IFN-α, IL-17 and TNF-α) but increased levels of the cytokine IL-10 in experimental allergic conjunctivitis and autoimmune arthritis models." (PMID 29975739, 2018). "The purpose of this study is to determine whether IL4, IL5 and IL13, players in allergic conjunctivitis, directly regulate mucin production in rat conjunctival goblet cells." (PMID 30111832, 2018). "A study reported increases in IL-1β, IL-2, IL-5, IL-6, IL-12, IL-13, in seasonal allergic conjunctivitis (SAC), vernal keratoconjunctivitis (VKC) and atopic keratoconjunctivitis (AKC), while IL-4, IFN-γ and IL-10 levels were increased in SAC and VKC compared to controls." (PMID 21298010, 2011).
amyloid (11 papers, 2015 to 2025). "In contrast, several studies have shown that immune activation by anti-inflammatory cytokines (i.e., IL-10, IL-4) is associated with exacerbation of amyloid pathology, though other studies show beneficial effects." (PMID 31822279, 2019). "In earlier studies, we reported that intracerebral expression of the anti-inflammatory cytokines, Interleukin-10 (Il10) and Interleukin-4 (Il4), increased amyloid β (Aβ) burden in TgCRND8 mice, a preclinical model of AD-type amyloidosis." (PMID 40055831, 2025). "According to one study a viral mediated overexpression of murine IL4 in the APP/PS1 mouse model of AD leads to a reduction of amyloid induced gliosis and amyloid peptide deposition together with improvement of neurogenesis." (PMID 32181251, 2020). "IL-1β increases IL-4 production, a potent modulator of CD4 T cell responses, and administration of IL-4 in AD mice induces amyloid plaque clearance." (PMID 31822279, 2019). "Based on our earlier studies that Il10 and Il4 worsen AD-amyloidosis, we reasoned that blocking the action of these cytokines within the brain could have a protective effect by acting as immune checkpoint inhibitors and preventing Aβ deposition." (PMID 40055831, 2025). "Administration of amyloid-specific Th2 cells improved spatial memory, decreased microglial reactivity and reduced Aβ pathology in AD animal models, pointing out the role played by IL4-producing cells in reducing AD damage." (PMID 32719583, 2020). "In mouse AD and amyloidosis models, the role of IL4 is controversial." (PMID 32181251, 2020). "Further studies are necessary to investigate whether the IL-4 signaling pathway cross-talk with TREM2 is involved in a protective microglial phenotype in response to amyloid pathology in AD models." (PMID 32959884, 2020). "This is consistent with in vitro findings that IL-4-treated microglia are potentially more efficient phagocytes, as well as an in vivo finding in which elevated Arg1 and reduced iNOS mRNA correlated with greater Aβ microglial phagocytosis and reduced amyloid plaque load." (PMID 26538310, 2015).
contact dermatitis (11 papers, 2019 to 2025). An inflammatory skin condition caused by direct contact between the skin and either an irritating substance or an allergen. "We found that participants with skin lesions in form of contact dermatitis caused by chronic exposure to silver and silica nanoparticles had higher genes expression of inflammatory cytokines, including IL4, IL6, IL8, and TNF-α compared to control individuals." (PMID 38454025, 2024). "DNCB is a substance that causes contact dermatitis through increasing serum immunoglobulin E (IgE) or Th2 cytokine levels (IL-4, IL-13, etc.)." (PMID 34944580, 2021). "Previously, we showed that the IJH-SONE68-derived EPSs significantly decrease the accelerated serum IgE level and the expression of IL-4 mRNA, in the contact dermatitis model mice." (PMID 34836277, 2021). "It has been also observed that the serum IgE and tissue IL-4 are increased in the contact dermatitis model mice." (PMID 31426284, 2019). "Likewise, EPSs from L. paracasei were able to reduce IgE and IL-4 levels in serum and ear tissue in a murine model of contact dermatitis, improving dermal health." (PMID 41301527, 2025). "In our model, the addition of DNCB and polarization of Th2 via IL4 may create a contact dermatitis or AD-like state that irritates dermal and epidermal cells, which leads to a pro-inflammatory environment." (PMID 38139083, 2023). "The treatment of mice subjected to contact dermatitis with polyphenols from pomegranate was followed by increasing splenic IL-10-producing and IFN-γ-/IL-4-producing CD4+ T cells." (PMID 36431972, 2022). "RT-PCR analyses also revealed mRNA upregulation of pro-inflammatory cytokines (IL-1β and IL-6) and some Th1 or Th2 cytokines (IFNγ, IL-4, and IL-10), but not that of IL-2, TGFβ, and IL-17, at the delayed phase of oxazolone-induced contact dermatitis, similar within the three genotypes." (PMID 36768979, 2023).
E. coli infection (11 papers, 2013 to 2025). "IFN-γ and TNF-α treatment in combination with C. rodentium and pathogenic E. coli infection negatively affected mucus parameters in vitro, which was relieved by IL-4 treatment." (PMID 30665337, 2019). "E. coli infection triggered a massive increase in transcript levels for Ccl2, iNos or Il6, a modest increase in Il10 transcripts but totally abrogated IL4 transcript expression in both Sham- and CLP-operated mice." (PMID 32425929, 2020). "Clinically source MDR E. coli strains infection caused serious systemic inflammatory response by sharply increasing the serum proinflammatory cytokines, such as TNF-α, IFN-γ, IL-6 (P < 0.05), and a significant reduction in IL-4 levels (P < 0.05) compared with the control group." (PMID 35250983, 2022). "However, E. coli infection before AAD phase suppressed Th2 cytokines IL-4 and serum IgE production, but in contrast enhanced Th1 cytokines IFN-γ and IL-2 production, Moreover, this effects were more significantly in the (108infN+OVA) group than the (106infN+OVA) and (108infA+OVA) group." (PMID 23536867, 2013). "Moreover, ABPS played a significant role in suppressing the effects of E. coli infection in the CABP group by lowering the concentrations of TNF-α and IL-4 compared to the CNG group." (PMID 30961158, 2018). "In these studies, E. coli infection increased the concentrations of pro-inflammatory cytokines (IFN-γ, TNF-α, IL-1β, IL-6 and IL-8) and decreased the concentrations of anti-inflammatory cytokine (IL-4), indicating that E. coli could induce inflammation in mice through regulation of cytokines." (PMID 33676495, 2021).
follicular lymphoma (11 papers, 2015 to 2025). Follicular lymphoma is a form of non-Hodgkin lymphoma characterized by a proliferation of B cells whose nodular structure of follicular architecture is preserved. "Recent evidence in follicular lymphoma further demonstrates that activating mutations in STAT6 sensitize tumor cells to IL-4, driving downstream mTOR pathway activation and compensating for CREBBP deficiency." (PMID 40864740, 2025). "In the comparison by subtype or GI lesions, serum interleukin (IL)-8 (P = 6.7E−05), IL-4 (P = 7.5E−05), and IL-1β (P = 0.0043) levels showed significant differences among subtypes, being particularly elevated in follicular lymphomas (FL) and mucosa-associated lymphoid tissue (MALT) lymphomas." (PMID 26674732, 2015). "In follicular lymphoma, these cells appear to provide IL-4 stimulation to the B cells and in conjunction with CD40 interactions, aid in the proliferation of neoplastic cells through STAT5 signaling." (PMID 30101129, 2018). "TFH cells have also been shown to provide support for the follicular lymphoma B cells through IL-4 and CD40 ligand production." (PMID 30101129, 2018).
HIV-1 infection (11 papers, 2014 to 2025). The type species of lentivirus and the etiologic agent of acquired immunodeficiency syndrome (AIDS). "Collectively, these findings indicated that GJB2 depletion using shRNA impaired the IL-4-mediated enhancement of HIV-1 infection." (PMID 40980890, 2025). "Herein, we found that IL-4 enhanced HIV-1 infection in myeloid lineage macrophages by downregulating the novel antiviral factor gap junction protein beta 2 (GJB2) located on the cell membrane." (PMID 40980890, 2025). "Here, we identified GJB2 as a novel antiviral factor by demonstrating that IL-4-mediated reduction in GJB2 levels enhanced HIV-1 infection in myeloid cells." (PMID 40980890, 2025). "Myeloid cells are collectively more resistant to HIV-1 infection than CD4+ T lymphocytes, but interleukin (IL)-4 has been observed to promote macrophage susceptibility to HIV-1 infection." (PMID 40980890, 2025). "IL-4 is a well-known promoter of HIV-1 infection in primary macrophages (18, –, 20) and reduces GJB2 expression in macrophages." (PMID 40980890, 2025). "With respect to HIV-1 infection, IL-4 was reported to differentially regulate two major HIV-1 coreceptors, CXCR4 for SI (syncytium-inducing) variants and CCR5 for NSI (no syncytium-inducing) viruses." (PMID 35632739, 2022). "MDM differentiated in the presence of IL-4 (termed M-4) were found to be more sensitive to HIV-1 infection, and to subsequent dissemination of HIV-1 to T cells, than MDM differentiated in IL-13 (M-13)." (PMID 32354203, 2020). "IL-4 is a product of activated T cells present in lymphoid tissues, including tonsils, where it enhances HIV-1 infection." (PMID 25330112, 2014). "Because of its favorable characteristic of inducing little homeostatic proliferation while efficiently enhancing HIV-1 infection, IL-4 is a useful alternative to IL-7 in such studies." (PMID 25330112, 2014). "First, we experimentally confirmed that IL-4 stimulated HIV-1 infection in primary macrophages." (PMID 40980890, 2025). "Because IL-4 downregulated GJB2 expression to enhance HIV-1 infection in macrophages, GJB2 may be a novel target for the treatment of HIV-1 infection." (PMID 40980890, 2025). "Individuals with HIV-1 infection show increased production of IL-4, the primary Th2-defining cytokine, as evidenced by an increased frequency of T cell clones with the Th2 phenotype and intracellular staining of IL-4 (35, –, 38)." (PMID 40980890, 2025). "Notably, IL-4 has also been reported to enhance HIV-1 infection in primary monocytes/macrophages (18, –, 20)." (PMID 40980890, 2025). "Thus, this investigation aimed to elucidate the mechanism of IL-4-mediated enhancement of HIV-1 infection." (PMID 40980890, 2025). "Therefore, IL-4 enhanced HIV-1 infection in myeloid lineage macrophages by downregulating the antiviral factor GJB2." (PMID 40980890, 2025). "HIV-1 infection is accompanied by dysregulation of cytokine production in vivo and in vitro, with downregulation of interleukin (IL)-2 and interferons and upregulation of proinflammatory cytokines IL-1, IL-4, IL-6, IL-10, and TNFα." (PMID 38280430, 2024). "The combination of these effects of IL-4 on HIV-1 replication may be involved in the phenotypic switch from NSI to SI as well as disease progression in HIV-1 infection." (PMID 35632739, 2022). "Interestingly, GJB2 silencing abrogated the IL-4-mediated enhancement of HIV-1 infection." (PMID 40980890, 2025). "Overall, our study provides insights into the ability of myeloid lineage cells to interfere with HIV-1 infection through GJB2 and partially answers the question of how IL-4 enhances infection by downregulating GJB2." (PMID 40980890, 2025). "Although myeloid cells are more resistant to HIV-1 infection than CD4+ T cells, some cytokines, including interleukin (IL)-4 and IL-6, promote myeloid cell infection." (PMID 40980890, 2025).
HIV-1 infection (continued). "In HIV infection, IL-4 differentially regulates the expression of CCR5 and CXCR4 co-receptors, which play a key role in HIV-1 infection, preventing the virus from entering the cell and its replication." (PMID 34835417, 2021). "Our findings showed that GJB2 silencing impaired IL-4- but not IL-6-mediated enhancement of HIV-1 infection, suggesting that IL-4-mediated downregulation of GJB2 expression enhanced HIV-1 infection." (PMID 40980890, 2025). "Our results showed that both IL-4 and IL-6 promoted HIV-1 infection without disrupting the GJB2 loci." (PMID 40980890, 2025). "In conclusion, HIV-1 infection shifts the cytokine profile from T-helper type 1 (TH1) towards T-helper type 2 (TH2), resulting in the excessive secretion of distinct cytokines, such as interleukin 4 (IL-4) and interleukin 10 (IL-10)." (PMID 37292193, 2023). "In the absence of GJB2 (in shGJB2), IL-4 (20 or 50 ng/mL) did not enhance HIV-1 infection." (PMID 40980890, 2025). "Additionally, unlike IL-4, the IL-6-mediated enhancement of HIV-1 infection in macrophages was unrelated to GJB2." (PMID 40980890, 2025). "Alternatively, polyclonal bystander activation of non-specific and low affinity B cells by cytokines and growth factors (e.g. IFN-a, TNF-a, IL-4, IL-10, BAFF) and surface CD40L, which may be over-expressed in untreated HIV-1 infection, may also affect the selection process." (PMID 24409278, 2014). "Therefore, IL-4 but not IL-6 downregulated GJB2 to promote HIV-1 infection in macrophages." (PMID 40980890, 2025). "However, IL-4 has been reported to enhance HIV-1 infection in primary monocytes/macrophages without affecting the expression of CC chemokine receptor 5 (CCR5), an HIV coreceptor (18, –, 20), but the underlying mechanism is unknown." (PMID 40980890, 2025). "In the absence of IL-4, GJB2 knockdown still promoted HIV-1 infection in macrophages (shCtrl vs shGJB2 without IL-4)." (PMID 40980890, 2025).